CKLF-CMTM1 (CKLF-CMTM1 readthrough)
Gene: Protein-coding gene on chromosome 16 (66,552,587 to 66,579,135, forward strand). Ensembl gene ENSG00000254788.
Genetic constraint (gnomAD): Loss-of-function variants: 14 observed, 10.92 expected, observed/expected ratio (o/e) 1.28, 90% interval 0.84 to 1.85. The upper end of that interval is the gene's LOEUF score, 1.85, which puts it in group 6 of 6, group 1 being the genes least tolerant of losing a copy. Missense variants: 189 observed, 227.71 expected, observed/expected ratio (o/e) 0.83, 90% interval 0.74 to 0.94. Synonymous variants: 84 observed, 89.79 expected, observed/expected ratio (o/e) 0.94, 90% interval 0.78 to 1.12.